DPH5 (diphthamide biosynthesis 5)
Description:
S-adenosyl-L-methionine-dependent methyltransferase that catalyzes four methylations of the modified target histidine residue in translation elongation factor 2 (EF-2), to form an intermediate called diphthine methyl ester. The four successive methylation reactions represent the second step of diphthamide biosynthesis.
Synonyms: AD-018; CGI-30; HSPC143; NPD015; NEDSFF
Tractability: PROTAC: ubiquitination databases record sites on it; its protein half-life has been measured.
Gene: Protein-coding gene on chromosome 1 (100,989,623 to 101,026,110, reverse strand). Ensembl gene ENSG00000117543.
Subcellular location (Human Protein Atlas): Golgi apparatus; Nucleoli
Pathways (Reactome):
Metabolism of proteins: Synthesis of diphthamide-EEF2
Gene Ontology:
Molecular function: diphthine methyl ester synthase activity; diphthine synthase activity; methyltransferase activity
Biological process: protein histidyl modification to diphthamide
Cellular component: cytosol
Genetic constraint (gnomAD): Loss-of-function variants: 19 observed, 21.53 expected, observed/expected ratio (o/e) 0.88, 90% interval 0.62 to 1.29. The upper end of that interval is the gene's LOEUF score, 1.29, which puts it in group 5 of 6, group 1 being the genes least tolerant of losing a copy. Missense variants: 260 observed, 295.71 expected, observed/expected ratio (o/e) 0.88, 90% interval 0.79 to 0.97. Synonymous variants: 104 observed, 105.56 expected, observed/expected ratio (o/e) 0.99, 90% interval 0.84 to 1.16.
Gene-disease validity (ClinGen):
ClinGen rates the evidence that DPH5 causes each of these diseases.
neurodevelopmental disorder with short stature, prominent forehead, and feeding difficulties (autosomal recessive): Limited. A neurodevelopmental disorder in which the cause of the disease is a mutation in the DPH5 gene.
Homologues: Orthologues: chimpanzee DPH5 (100% identical), macaque DPH5 (97% identical), pig DPH5 (93% identical), mouse Dph5 (91% identical), rat Dph5 (91% identical), dog DPH5 (91% identical), guinea pig DPH5 (88% identical), rabbit DPH5 (76% identical), zebrafish dph5 (75% identical), tropical clawed frog dph5 (69% identical), Drosophila melanogaster Dph5 (61% identical), Caenorhabditis elegans dph-5 (60% identical).
Diseases named in the same sentence as DPH5 in open-access papers:
DPH5 is named in the same sentence as 9 diseases in open-access papers, as found by Europe PMC text mining. Sharing a sentence is not in itself a finding about the gene and the disease. The quoted sentences say what the papers report.
developmental delay (1 paper, 2025). "Loss-of-function (LoF) mutations in genes involved in diphthamide biosynthesis, such as DPH1, DPH2, and DPH5, result in developmental delay (DD), intellectual disability (ID), and multisystemic abnormalities." (PMID 40725455, 2025).
inflammatory bowel disease (1 paper, 2020). A spectrum of small and large bowel inflammatory diseases of unknown etiology. "The genes DPH5 and DAP3 are co-expressed and associated with inflammatory bowel disease (IBD)." (PMID 32652930, 2020).
RASopathy (1 paper, 2025). Developmental syndromes caused by germline mutations (or in rare cases by somatic mosaicism) in genes that alter the Ras subfamily and mitogen-activated protein kinases that control signal transduction. "Although a strict interaction between DPH5 and the RAS-MAPK pathway is not apparent, indicating the DPH5-related condition as a RASopathy “phenocopy”, Dph5 knockdown was demonstrated to ameliorate the pathogenic phenotypes in an in vitro model of Ras-induced tumor." (PMID 40725455, 2025).
cancer (2 papers, 2021 to 2025). A tumor composed of atypical neoplastic, often pleomorphic cells that invade other tissues. "Across all cancer cell lines, we observed that many more genes were depleted rather than enriched in these screens, with DPH5, ZNF124, ABL1, and HNF4A showing the most significant toxicity." (PMID 39870664, 2025). "ROC curve analyses revealed that methylation status of each individual genes could significantly distinguish primary carcinoma from adjacent normal mucosa, as measured by AUC value (DLX6-AS1: 0.941; lnc-DPH5-1: 0.833; lnc-PRSS2-6: 0.913; lnc-RPS12-6: 0.916; lnc-SFRP4-2: 0.830; SOX21-AS1: 0.921)." (PMID 35127488, 2021).
tumor (2 papers, 2017 to 2025). "We have applied assays based on the recombinant complementation of DPH gene deficiency in tumor cells to address the functionality of DPH1 and DPH5 variants." (PMID 28245596, 2017). "Except for analyses performed on recombinant cells lacking DPH5, the functionality of isoforms and protein variants and their impact on the efficacy of tumor-targeted ADP-ribosylating toxins is unknown." (PMID 28245596, 2017). "Because of that, rare variations in the DPH5 gene may not play a significant role in determining the sensitivity of tumor cells to targeted toxins (as inactivation of both functional alleles will be extremely rare)." (PMID 28245596, 2017).
genetic disorder (1 paper, 2025). "DPH5-related diphthamide deficiency syndrome is a recently identified and still poorly defined genetic disorder, with only five patients reported in the literature to date." (PMID 40725455, 2025).
DPH5 also shares sentences with these, for which no sentence is quoted: colorectal cancer (1 paper); epilepsy (1); Intellectual disability (1).